TNF (tumor necrosis factor)
Diseases named in the same sentence as TNF in open-access papers (continued):
Sharing a sentence is not in itself a finding about the gene and the disease.
bladder cancer (continued). "The presence of TNF+488A was significantly higher in the first set of bladder cancer patients compared with controls." (PMID 12966432, 2003). "There is considerable direct and indirect evidence to implicate TNFα in the development of bladder cancer." (PMID 12966432, 2003). "Overall, these results suggest the regulation of the TNF signaling pathway by Disitamab Vedotin at the mRNA level in bladder cancer cells and also indicate that different bladder cancer cell lines may respond slightly differently to Disitamab Vedotin." (PMID 40699768, 2025). "Therefore, in this study, we aimed to investigate the relationship between miRNA-21, miRNA-155, miRNA-34a, IL-6, TGF-β, and TNF-α proinflammatory cytokines, and serum iron, copper, and zinc levels with the early diagnosis and progression of bladder cancer." (PMID 41614883, 2025). "TNF is an important inflammatory mediator, which can promote the release of pro-inflammatory factors and also plays an important role in the occurrence and development of bladder cancer." (PMID 41287122, 2025). "In addition, the combined effect of TNF and ionising radiation on the induction of apoptosis in bladder cancer cells was demonstrated." (PMID 38874510, 2024). "In addition, HCS attenuated the proliferation of bladder cancer cells by regulating the Fas/Fasl and TNF-α/TNFR1 pathways." (PMID 38753638, 2024). "We speculate that BCG-induced contact-dependent macrophage killing also takes place in patients with cancer, as the abundance of TNF in the urine of patients with bladder cancer is markedly increased after BCG instillation." (PMID 39114912, 2024). "In this study, we found that TAM infiltration could enhance the resistance of bladder cancer to cisplatin through TNF‐α secretion." (PMID 38750006, 2024). "Thus, LINC00702-activated DUSP1 suppresses bladder cancer cell proliferation and inhibits the secretion of inflammatory cytokines IL-4, IL-10, and TNF-α M2-OAM in bladder cancer." (PMID 38139370, 2023). "It is believed that BCG stimulation of TNFα production by either bladder cancer cells or host immune cells could trigger the apoptosis of bladder cancer when an IAP antagonist is given to degrade the IAP proteins." (PMID 36119107, 2022). "Bladder cancer is considered to be highly related to inflammation and hydrogen peroxide and several cytokines, including interleukin (IL) 1α, IL-6 and tumor necrosis factor-α (TNFα) accumulate during inflammation, driving bladder carcinogenesis." (PMID 34073079, 2021). "Pathway enrichment analysis by clusterProfiler R package showed that the up-regulated genes obtained by overexpressing U11 were mainly enriched in regulation of mast cell degranulation, chemokine activity, NF-kappa B signaling pathway, TNF signaling pathway, and Bladder cancer, etc.." (PMID 34276798, 2021). "KEGG enrichment analysis totally obtained 6 pathways, namely, bladder cancer (hsa05219), pathways in cancer (hsa05200), chemical carcinogenesis (hsa05204), estrogen signaling pathway (hsa04915), TNF signaling pathway (hsa04668), and leukocyte transendothelial migration (hsa04670)." (PMID 32849897, 2020). "The progression of DNA repair and cell proliferation in stage 1 bladder cancer ultimately results not only in the derepression of miR-200a and miR-200b but also in the regulation of the TNF pathway to metastasis-related genes or proteins, cell proliferation, and DNA repair in stage 4 bladder cancer." (PMID 27034531, 2016). "HCS could efficiently inhibit proliferation and induce apoptosis in human bladder cancer cells in vitro and in vivo, which is largely mediated by Fas/Fasl and TNF- alpha/TNFR1 pathway." (PMID 25887782, 2015). "In human bladder cancer cells, TNF-alpha could stimulate the secretion of matrix metalloproteinase-9 (MMP9) which has been implicated in tumor invasion and metastasis." (PMID 22811589, 2012). "IL1b, IL6, GMCSF, MCSF, GCSF, and TNFα are expressed in a human bladder carcinoma cell line." (PMID 22013484, 2011).
bladder cancer (continued). "In addition to the killing of bladder cancer cells, both TNF-α and IFN-γ are also known to work through autocrine for macrophage activation and NO production." (PMID 20862387, 2010). "Therefore, we propose evaluation of the effectiveness on tumor reduction of rBCG-S1PT, compared to BCG and PBS; and evaluation of the immune response profile focusing on TNF-α (Th1) and IL-10 (Th2) in an orthotopic bladder cancer animal model." (PMID 19040745, 2008). "Given the key role of TNFα in angiogenesis and tumour development, the aim of this study was to investigate whether polymorphisms in TNF alter the risk of developing bladder cancer and subsequent tumour behaviour." (PMID 12966432, 2003). "In angiogenesis, TNFα is known to play a key role in the regulation of the enzyme thymidine phosphorylase, which in turn has been demonstrated to be a component in bladder cancer progression." (PMID 12966432, 2003). "For instance, SLURP1 has been shown to reduce TNF-α-induced NF-κB activation, thereby suppressing inflammatory responses an anti-inflammatory function that might be important in the bladder cancer microenvironment and SLURP1 can also stabilize epithelial cell junctions." (PMID 40740240, 2025). "Additionally, TNF-α plays a significant role in the preventive effects against bladder cancer." (PMID 40006511, 2025). "Additionally, TNF-α is an important mediatorof BCG-stimulated neutrophil-mediated tumor cell death in combinationwith a DIABLO/SMAC mimetic in the RT4v6 bladder cancer cell line.It mediates cell death and IL-1 release, mediating the cytotoxic activityof CAR-T cells." (PMID 40047620, 2025). "Notably, this study found that the expression levels of AKT1, GSK3B, CASP3, TNF, and CCND1 were associated with immune cell infiltration in bladder cancer, suggesting that these targets could be used as potential predictors of bladder cancer immunotherapy." (PMID 41287122, 2025). "The results showed that bladder cancer (hsa:05219), platinum drug resistance (hsa:01524), prolactin signaling pathway (hsa:04917), small cell lung cancer (hsa:05222), IL-17 signaling pathway (hsa:04657), and TNF signaling pathway (hsa:04668) were highly enriched." (PMID 37759722, 2023). "Notably, cisplatin treatment significantly promoted the expression of these cytokines in GFP-knockdown but not Hotair-knockdown cells, indicating that knockdown of Hotair abolished cisplatin-induced upregulation of IL-6, TNF-α, and IL-1β in mouse bladder cancer cells." (PMID 36471329, 2022). "TNF-α and p21 may both play an important role in the prevention of bladder cancer." (PMID 36364214, 2022). "Interestingly, we found that both up-regulated genes in the U11 overexpression group and down-regulated genes in the U11 knockout group were mainly enriched in cancer-related pathways, such as NF-kappa B signaling pathway, TNF signaling pathway and Bladder cancer." (PMID 34276798, 2021). "However, the expression patterns, prognostic values, and immunological characteristics of TNF members in bladder carcinoma (BLCA) remain unclear." (PMID 35174161, 2021). "To determine whether Fas/Fasl and TNF-α/TNFR1 expression is critical for the effect of HCS on bladder cancer cells, we knocked down TNF-a, TNFR1, Fas by siRNA or inhibited binding of FasL to its receptor by a blocking antibody (ZB4) prior to the addition of HCS, and then detected the cell viability." (PMID 25887782, 2015). "It is possible that upregulation of TNFα or TNFα-dependent pathways direct the progression of bladder cancer to grade 2, but other additional factors are involved in progression from grade 2 to grade 3, in keeping with the evidence of stepwise progression of bladder cancer." (PMID 12966432, 2003).
bladder cancer (continued). "RAC-alpha serine/threonine-protein kinase 1 (AKT1), glycogen synthase kinase 3 beta (GSK3B), caspase-3 (CASP3), tumor necrosis factor (TNF) and cyclin D1 (CCND1) were identified as the main hub targets of COP in bladder cancer treatment." (PMID 41287122, 2025). "Using real-time single-cell-resolution microscopy, we demonstrate in vivo in a bladder cancer zebrafish xenograft that BCG immunotherapy induced cancer cell apoptosis and clearance of tumors through macrophages and TNF signaling." (PMID 39114912, 2024). "As for cell viability, our previous research on bladder cancer also demonstrated that WWOX decreases mitochondrial redox potential, with the explanation for this possibly to be found in the link between TNF and reactive oxygen species." (PMID 36979157, 2023). "Cytokines released in patients with bladder cancer treated with BCG include TRAIL (TNF-related apoptosis-inducing ligand), IL-2, IL-8, IL-18, IL-12, IFN-γ, and TNFα." (PMID 36119107, 2022). "Long-term accumulation of toxins and glycation end products in patients with bladder cancer will increase the body's inflammatory factors, such as IL-6, CRP, TNF-α, and other acute reactive proteins." (PMID 35075365, 2022). "In vitro study confirmed that urinary bladder cancer HT1376 cells were, via increased secretion of MMP-9, stimulated by TNF-α." (PMID 33923108, 2021). "Interestingly, in the HT-1376 bladder cancer cell line, the potentiation of birinapant and gemcitabine treatment was not attenuated by co-treatment with an anti-TNF antibody, thus indicating that the increase in cell death was via a TNF-independent-mechanism in this tumor." (PMID 32053868, 2020). "In contrast to unarmed ATCs, CD155Bi-armed ATCs against bladder cancer cells were increased cytotoxic activity at effector/target (E/T) ratios of 5:1, 10:1, and 20:1, with more IFN-γ, TNF-α secreting." (PMID 31602268, 2019). "The results showed that ATC with B7‐H3Bi‐Ab had significant cytotoxic activity on human bladder cancer cells compared with ATC alone and unarmed ATC, probably due to the secured secreted higher level of IFN‐γ and TNF‐α." (PMID 30253078, 2018). "p38 MAPK mediates TNFα-induced MMP-9 expression, thus leading to the progression of human urinary bladder cancer cells." (PMID 21859479, 2011). "Both direct effector-target cell contact and release of soluble cytotoxic factors (such as TNF-α,IFN-γ and NO) are required for effective killing of bladder cancer cells by BCG-activated macrophages." (PMID 20862387, 2010). "We thus proposed the evaluation and comparison of the immune balance responses of TNF-α and IL-10 to rBCG-S1PT and BCG in an animal model of orthotopic bladder cancer." (PMID 19040745, 2008). "AKT1, GSK3B, CASP3, TNF, CCND1 are the main targets of COP in the treatment of bladder cancer." (PMID 41287122, 2025). "In this study, through network pharmacology, it was demonstrated that AKT1, GSK3B, CASP3, TNF, and CCND1 may be the crucial targets of COP in bladder cancer treatment." (PMID 41287122, 2025). "The ERH gene might affect the apoptosis of bladder cancer T24 cells through TLR, NF-κB, TNF, or TGF-β signaling pathways, activating the growth of malignant tumors." (PMID 33552118, 2020).
bladder cancer (continued). "Moreover, we found that silencing LINC00482 inhibited inflammation and angiogenesis in bladder cancer through the down-regulation of MMP-15 by targeting FOXA1, along with decreased levels of TNF-α, IL-1β, and IL-6 as well as the expression of VEGF and NF-κB." (PMID 33323547, 2020). "In bladder cancer, neutrophils exhibited impaired killing, whereas neutrophils from patients with oral cavity cancer secreted higher levels of VEGF and diminished levels of soluble tumor necrosis factor (TNF)-related apoptosis-inducing ligand." (PMID 28220123, 2017). "The data revealed a significant increase in TNF-α level in bilharzial and non-bilharzial bladder cancer patients versus normal controls." (PMID 21473769, 2011). "CytoNCA plug-in analysis showed that the PI3K-Akt signaling pathway (degree = 9) may be the key pathway in the treatment of bladder cancer by COP, and AKT1 (degree = 12), GSK3B (degree = 10), CASP3 (degree = 10), TNF (degree = 8) and CCND1 (degree = 8) were considered to be the main hub targets." (PMID 41287122, 2025). "For instance, in bladder cancer, elevated expression of ST6GALNAC1 correlated with increased immature dendritic cells (DCs) unresponsive to further maturation stimuli and low levels of Th1-inducing cytokines IL-12 and TNF-α, resulting in T cells exhibiting a phenotype indicative of tolerance." (PMID 41152402, 2025). "Research has demonstrated that inflammatory cytokines (e.g., IL-6, TNF-α) can inhibit erythrocyte maturation, leading to increased RDW, while simultaneously activating oncogenic pathways such as STAT3, promoting tumorigenesis, immune evasion, and driving bladder cancer progression." (PMID 41561745, 2025). "Due to the functional roles of TNF-α in the proliferation, activation, and differentiation of cancer and immune cells, regulation of TNF-α expression levels might be an important strategic approach for the development of effective treatments against bladder cancer." (PMID 41614883, 2025). "Additionally, we did not further explore the function and significance of TNF signaling pathway activation in bladder cancer cells exposed to Disitamab Vedotin, which could be a direction for future research." (PMID 40699768, 2025). "The current work was also extended to study the inflammatory cytokine, tumor necrosis factor - alpha (TNF-α) in bilharzial and non-bilharzial bladder cancer patients." (PMID 21473769, 2011).
Hyperinsulinemia (149 papers, 2009 to 2026). An increased concentration of insulin in the blood. "IL-6 can promote the production and secretion of insulin in prediabetes, leading to the occurrence of hyperinsulinemia, which is associated with TNF- α." (PMID 41098781, 2025). "Treatment of cells with pathologic concentrations of TNFα or with high nutrients also caused a decrease in insulin-stimulated IR incorporation into puncta similar to that observed for hyperinsulinemia." (PMID 36473871, 2022). "Increased TNF-α concentrations are closely associated with hyperinsulinemia and body mass index (BMI)." (PMID 35627115, 2022). "TNF is also expressed by adipocytes; its expression is higher in adipose tissue from obese vs. lean humans, and high levels are associated with hyperinsulinemia and IR." (PMID 34103691, 2021). "The present study showed that the HF diet induced an increase of TNF-α and IL-6 pro-inflammatory cytokines plasma level and a decrease of IL-4 and IL-10 anti-inflammatory cytokines plasma level, associated with hyperinsulinemia and a high HOMA-IR index." (PMID 31091691, 2019). "In abdominal obesity, high circulating TNF-α levels are associated with hyperinsulinemia and IR57." (PMID 36922570, 2023). "Hyperinsulinemia leads to increased ROS, which further increases the production of inflammatory cytokines, including TNF-α, monocyte chemoattractant protein-1, interleukins, or prostaglandins." (PMID 36829437, 2023). "Hyperinsulinemia or the low-grade inflammation and changes in proinflammatory/anti-inflammatory cytokines (i.e., TNF α, IL-1 β, and adiponectin) are also derived from adipose tissue." (PMID 36045779, 2022). "Compared with adipose tissue in lean subjects, TNF-α expression is many times higher in obese subjects in correlation with hyperinsulinemia." (PMID 34680177, 2021). "Factors that decrease the level of ANGPTL8 includes hyperinsulinemia, TNFα, miRNA 143-3p from hepatocytes, and miRNA 221-3p which expression is promoted by activated macrophages in adipose cells, glucocorticoids during fasting, etc.." (PMID 32537470, 2020). "There is a positive correlation between the mRNA expression level of TNF‐α and hyperinsulinemia in AT." (PMID 33278072, 2020). "Recent studies show that diabetogenic factors, such as free fatty acid (FFA), TNF-α and hyperinsulinemia, increase the serine phosphorylation of IRS-1, and ser307/612/632 were identified as phosphorylated sites." (PMID 30871060, 2019). "Among women with GDM, higher amounts of TNF-α are secreted by placenta and adipose tissues in response to high glucose and hyperinsulinemia." (PMID 29385062, 2018). "Treatment of 3T3-L1 adipocytes with 10 nm insulin for 24 h to mimic hyperinsulinemia or with 2 ng/ml TNFα for 96 h to mimic chronic pro-inflammatory signaling impaired insulin-stimulated 2-deoxyglucose (2DOG) uptake." (PMID 29599292, 2018). "mRNA expression in adipose tissue of the TNF-α of obese subjects is 2.5 times greater than in subjects with normal weight, and this high expression level is greatly correlated with hyperinsulinemia." (PMID 26366171, 2015). "A MO diet resulted in maternal hyperinsulinemia and hyperleptinemia and increased plasma glucose, glutamate and TNF-α concentrations." (PMID 24146946, 2013). "In comparison to LS alone, ET was more effective in attenuating the degree of adiposity, hyperinsulinemia and circulating levels of TNF-α." (PMID 21899736, 2011). "We report that hyperinsulinemia augmented TNFα stimulated increases in VCAM-1 protein greater than seen with TNFα alone and decreased the time in which VCAM-1 translocated to the cell surface." (PMID 22093181, 2011). "We showed that the specific combination of RIAA : PAC (1 : 5) synergistically increased TG content in 3T3-L1 adipocytes under conditions of hyperinsulinemia and increased adiponectin secretion in cells treated with TNF-α." (PMID 20721358, 2010).